TWIST1 (twist family bHLH transcription factor 1)
Diseases named in the same sentence as TWIST1 in open-access papers (continued):
Sharing a sentence is not in itself a finding about the gene and the disease.
melanoma (continued). "Epithelial to mesenchymal transition (EMT)-like processes enable melanoma cells to disseminate from the primary site and this is orchestrated by the main transcription factors Snail, Slug, ZEB1 and Twist1, whereas their repression is required to promote metastatic growth in vivo." (PMID 38419052, 2024). "What's more, LOXL3 could also regulate the metastasis of melanoma via affecting the expression of MITF, TWIST1, SNAIL1 and PRRX1, which were molecules that involved in EMT process." (PMID 36324258, 2022). "In melanoma, TWIST1 directly inhibits CADM1 expression by interacting with the E-box in the CADM1 promoter region and promotes EMT phenotype conversion, which aggravates migration and invasion of melanoma cells." (PMID 34395444, 2021). "In addition, western blot analysis further validated key changes at the protein level, with TWIST1, c-MET and β1-integrin levels dramatically increasing after induction of BRN2 expression in three of three melanoma cell lines." (PMID 32632141, 2020). "Moreover, intra-tumor heterogeneity was observed within human primary melanoma lesions by immunohistochemical analyses: opposite gradients in the expression of ZEB2/SNAIL2 and TWIST1/ZEB1 were observed from superficial to deep sites." (PMID 32759677, 2020). "Indeed, ZEB1 and TWIST1 have been shown to downregulate MITF whereas SNAIL2 or ZEB2 induce MITF expression, demonstrating that these EMT-TFs act as key players in melanoma phenotype switching." (PMID 32858889, 2020). "The protein levels of the FRA1 transcription factor, a known inducer of ZEB1 in melanomas, also increased, whereas TWIST1 was not affected." (PMID 27596438, 2016). "In this study, we suggest that Twist1 and STAT3 activation contribute to melanoma migratory and invasive abilities because overexpression of Twist1 or STAT3 enhanced cell migratory and invasive abilities, and also reversed apigenin-mediated melanoma migration and invasion inhibition." (PMID 26911838, 2016). "The negative correlations between miR-33b levels and HMGA2, Twist1 or ZEB1 expression were detected in 72 patient melanoma tissue samples." (PMID 25868853, 2015). "QRT-PCR experiments showed that naïve 501mel melanoma cells exposed to the secretome of melanoma cells rendered senescent by MITF silencing exhibited an increased level of SNAIL1, TWIST1, Fibronectin1, N-Cadherin (CDH2) mRNAs whereas MITF and E-Cadherin (CDH1) transcripts were markedly decreased." (PMID 24344100, 2013). "Furthermore, gene expression of LRRC15 and TWIST1 clearly does not correlate in several cancer types such as adrenocortical carcinoma or melanoma." (PMID 37534184, 2023). "Indeed, ZEB1/TWIST1 are expressed in the bulk of primary melanoma and ZEB1 ectopic expression promotes tumorigenic features in melanoma cell lines, while its knock-down drastically decreases the tumorigenic growth of melanoma cells in vivo upon xenograft in nude mice." (PMID 32759677, 2020). "We also studied human melanoma datasets from The Cancer Genome Atlas (TCGA), and found that the TET proteins, especially TET2 were downregulated, and the mesenchymal marker Vimentin and EMT master transcription factors like ZEB2, SNAIL2 and TWIST1 were up regulated." (PMID 27852070, 2017). "However, the ectopic expression of TWIST1 did not significantly stimulate the colony formation capacity of melanoma cell lines, suggesting that ZEB1 is a stronger oncogenic factor than TWIST1 in this tumor type." (PMID 27596438, 2016). "Therefore, we asked whether cordycepin can inhibit melanoma migration by targeting miR-33b and downregulating HMGA2 and Twist1 expression." (PMID 25868853, 2015). "Using linear regression analysis, miR-33b displayed a significant negative correlation with the expressions of HMGA2, Twist1 and ZEB1, consistent with these genes being regulated by miR-33b in melanoma." (PMID 25868853, 2015).
melanoma (continued). "Importantly, Notch4 may induce suppression of Snail2 and Twist1 through downstream Hey1 and Hey2 targets and is non-canonically mediated in WM9 and WM164 melanoma cell lines." (PMID 37108670, 2023).
ovarian carcinoma (75 papers, 2010 to 2025). A malignant neoplasm originating from the surface ovarian epithelium. "miR-186 was similarly linked to a reduction in TWIST1 and a reversal of platinum resistance in ovarian cancer." (PMID 38139368, 2023). "MiR-186 downregulation was associated with EMT and chemoresistance by targeting Twist1 in ovarian cancer cell lines." (PMID 36984544, 2023). "We previously demonstrated that COL11A1-mediated nuclear factor-κB activation promoted the expression of TWIST1 and Mcl-1, factors associated with chemoresistance and anti-apoptosis in ovarian cancer cells." (PMID 30975980, 2019). "Finally, we addressed whether the LPA-promoted signature associated with Hh (GLI1, BMI1) and EMT (SNAI1, TWIST1) genes has an impact on the clinical outcome of ovarian cancer patients." (PMID 34831435, 2021). "Further, CBX7 has been demonstrated to render TWIST-1 transcriptionally inactive during the mesenchymal-epithelial transition (MET) in ovarian cancer." (PMID 40175347, 2025). "The miR-15a-3p has been shown to suppress proliferation and migration inhibiting the expression of BCL2 and MCL1 in epithelial cells and restrains the growth and metastasis of ovarian cancer cells by regulating Twist1." (PMID 36012492, 2022). "We have reported that TWIST1 is an important regulator of “stemness” in epithelial ovarian cancer (EOC) cells." (PMID 36123378, 2022). "To further determine the correlation between TWIST1 and β-catenin expression, we treated ovarian cancer cells with TWIST1 siRNA and measured the protein levels of β-catenin and TWIST1." (PMID 36123378, 2022). "To investigate the role of TWIST1 during the differentiation process of ovarian cancer stem-like cells, we performed an EMT array in primary EOC cells, MSFCs, and sEOC cells." (PMID 36123378, 2022). "It is associated with the transition of epithelial stem-like Type I/CD44+ EOC cells to mesenchymal Type II/CD44- EOC cells, suggesting that TWIST1 regulates ovarian cancer cell differentiation." (PMID 36123378, 2022). "This is corroborated by reduced miR-199a/miR-214 expression following Twist1 knockdown in ovarian cancer cells." (PMID 34943783, 2021). "Collectively, the present study demonstrates that ATX, and thereby LPA, induces DDR2 expression through the activation of the PI3K/Akt/mTOR/HIF-1α/Twist1 signaling axes, aggravating ovarian cancer cell invasion." (PMID 34065317, 2021). "The schematic signaling pathway of LPA-induced DDR2 expression depicts the upregulation of DDR2 by LPA through coordinate activation of the PI3K/Akt/mTOR/HIF-1α signaling pathways and Twist1 expression to augment ovarian cancer cell invasion." (PMID 34065317, 2021). "Suppression of Twist1 expression by introducing miR-186 renders the ovarian cancer cells to overcome cisplatin resistance." (PMID 33768509, 2021). "For instance, twist-related protein 1 (Twist1)-mediated upregulation of miR-199a/214 has been shown to be essential for the transformation of ovarian cancer stem cells (Type I/CD44+) into mature, fast-dividing cancer cells (Type II/CD44−)." (PMID 32850313, 2020). "In ovarian cancer cells, the L1CAM gene was found to be under the regulation of TWIST1, a transcription factor that is causally linked to increased tumorigenicity as well as resistance to cisplatin." (PMID 32429448, 2020). "Twist1 upregulation is observed in a variety of cancer types, including OS as well as breast, bladder, gastric, and ovarian cancer." (PMID 32391253, 2020). "A previous study has reported that the Dnm3os locus is regulated by TWIST1, which promotes cancer stemness, inflammation, and proliferation of human ovarian cancer cells." (PMID 32019274, 2020). "In chemoresistant ovarian cancer cells, inhibition of Akt phosphorylation, resulted in p70S6K inactivation and TWIST1 downregulation." (PMID 31331001, 2019). "We observed that knockdown of TWIST1 resulted in significantly reduced levels of DNM3OS in SKOV3 ovarian cancer cells (two-tailed t-test P < 0.008)." (PMID 29150601, 2017).
ovarian carcinoma (continued). "Our results together with previously published data indicate TWIST1 regulates the expression of DNM3OS in ovarian cancer cells." (PMID 29150601, 2017). "Cisplatin-resistant ovarian cancer cell lines exhibit decreased miR-186 expression and increased Twist1 expression while the introduction of miR-186 can reverse drug resistance through Twist1 down-regulation." (PMID 28099910, 2017). "Expression data also indicate a significant positive correlation between DNM3OS and TWIST1 expression in ovarian cancer." (PMID 29150601, 2017). "This study is the first to focus on the specific mechanisms by which TWIST1 confers cisplatin drug resistance in ovarian cancer, a novel function for a transcription factor that has previously primarily been only associated with tumour cell motility." (PMID 27876874, 2016). "In ovarian cancer, Twist1 overexpression promotes the expression of N-cadherin and reduces the expression of keratin-8 and E-cadherin." (PMID 26356073, 2015). "As described for other solid tumors, TWIST1 is thought to play an important role in the metastatic process of ovarian cancer." (PMID 25238494, 2014). "We will discuss first the broader findings on the role of TWIST1 in ovarian cancer and then we will review the role of TWIST1 in ovarian cancer stem cells." (PMID 25238494, 2014). "One of the first reports linking TWIST1 and ovarian cancer was the study from Kajiyama and colleagues." (PMID 25238494, 2014). "Since then, several studies have been conducted to elucidate the function of TWIST1 in ovarian carcinomas." (PMID 25238494, 2014). "The following novel insights exemplify the importance and potential link between cancer stem cells and TWIST1 in the progression of ovarian cancer, and serve as a framework for understanding the role of TWIST1 in ovarian cancer." (PMID 25238494, 2014). "We discuss the potential role of TWIST1 in the context of ovarian cancer stem cells and its influence in the process of tumor formation." (PMID 25238494, 2014). "The objective of this review is to examine the normal functions of TWIST1 and its role in tumor development, with a particular focus on ovarian cancer." (PMID 25238494, 2014). "While the control of metastasis is one area of TWIST1's involvement in ovarian cancer, it is also involved in another important phenomenon – chemoresistance." (PMID 25238494, 2014). "Conversely, increased TWIST1 expression and a concomitant reduction in PTEN and IKKβ activity was observed in differentiated ovarian cancer cells, indicating that TWIST1 regulates ovarian CSC/TIC differentiation." (PMID 23528891, 2013). "A recent study reported that twist-related protein 1 (TWIST1) is involved in the differentiation of ovarian CSC/TICs (type I/CD44+ cells) isolated from either ovarian ascites or ovarian cancer tissues." (PMID 23528891, 2013). "Additionally, CBX7 can inhibit TWIST1 by binding to the E-box sequence, which reduces the metastatic potential and tumorigenicity of secondary epithelial ovarian cancer in vitro and in vivo." (PMID 40175347, 2025). "Twist1 promotes ovarian cancer metastasis by upregulating discoidin domain receptor 2 (DDR2), a receptor tyrosine kinase (RTK) that recognizes fibrillar collagen as a ligand and enhances mesothelial clearance, invasion, and migration through matrix remodeling and Snail1 stabilization." (PMID 39796130, 2024). "DDR2 has been reported to be induced by TWIST1 in ovarian cancer." (PMID 36713812, 2022). "Interestingly, DDR2 is a key transcriptional target of TWIST1 during cranial mesoderm development and in ovarian cancer cells, where TWIST1-dependent DDR2 expression was critical for EMT, migration, invasion, and in vivo metastasis." (PMID 34716856, 2022). "Interestingly, TWIST1 has been reported to regulate DDR2 expression in ovarian cancer and was found to be a shared effector of FOXQ1 and SNAI1 in this study." (PMID 36713812, 2022).
ovarian carcinoma (continued). "Furthermore, the silencing of Twist1 expression significantly inhibited LPA-induced ovarian cancer cell invasion." (PMID 34065317, 2021). "Similarly, resistance to paclitaxel by Twist1 overexpression occurs in human nasopharyngeal carcinoma cells, bladder, and ovarian cancer cells." (PMID 33768509, 2021). "TWIST1, acting as an epithelial-mesenchymal transition transcriptional regulator, plays an important role in escaping apoptosis and metastasis, with increased expression stepwise from benign, borderline, to malignant ovarian tumors." (PMID 33921111, 2021). "In addition, COL11A1 interferes with anti-cancer drug-induced apoptosis in ovarian cancer cells by upregulating TWIST1-mediated Mcl-1 expression." (PMID 30975980, 2019). "TWIST1 is overexpressed in ovarian cancer and a known ovarian cancer EMT marker." (PMID 29150601, 2017). "This is the first study on the role TWIST1 plays in acquired drug resistance in ovarian cancer." (PMID 27876874, 2016). "In ovarian cancer, TWIST1 protein is degraded in CSCs, maintaining CSCs in an epithelial state." (PMID 27876874, 2016). "Despite its known role in activation of the stem cell pool, the direct role of TWIST1 in drug resistance in ovarian cancer is relatively unknown." (PMID 27876874, 2016). "In addition, Twist1 was shown to induce DDR2 expression in ovarian cancer." (PMID 34065317, 2021). "Similarly, miR-320 repressed oncogenicity of ovarian cancer by targeting TWIST1 expression." (PMID 33024414, 2020). "Key findings include the identification of core EMT regulators, such as TWIST1, SNAIL, and ZEB1, which are upregulated in both ovarian cancer and GBM, promoting mesenchymal phenotypes and metastasis." (PMID 39936963, 2025). "Similar to CNC, ovarian cancer cells secrete C3, which is induced in these cells by the EMT factor Twist1 and is expressed at the invasive edge of metastatic cells in vivo." (PMID 37489330, 2023). "Both HIF1A and TWIST1 are integral to the PI3K pathway, which was described to be crucially involved in the tumorigenesis of ovarian cancer." (PMID 37370765, 2023). "DAB2 expression had significant positive correlations with mesenchymal markers (ZEB2, TGFβ1, SNAI2, ZEB1, FN1, MMP2, TWIST1 and MMP3) and CSC markers (CD44 and MYD88) in ovarian cancer cell lines (CCLE) and tissues (TCGA: RNA sequencing and microarray)." (PMID 37815603, 2023). "LYC down‐regulates the expression of EMT markers including Twist family BHLH transcription factor 1 (TWIST) and Snail in ovarian cancer cell‐borne mice compared to those receiving placebo treatment." (PMID 37070131, 2023). "This is the first study to unveil the relationship between TWIST1 and AXIN2 and provides a new perspective to understand the differentiation process of ovarian cancer." (PMID 36123378, 2022). "Protein expression levels of E-cadherin, VIMENTIN, ZO-1, TWIST-1 and PAR6α were assessed in total protein lysates and protein expression levels of SNAIL1 were assessed in nuclear lysates, respectively, in multiple ovarian cancer cell lines." (PMID 35379775, 2022). "Twist1 is believed to drive cisplatin resistance via upregulation of L1CAM, GAS6, and Akt signaling pathways in an ovarian cancer model." (PMID 33768509, 2021). "Twist basic helix loop helix transcription factor 1 (Twist1), a regulator of EMT, is upregulated in cisplatin-resistant ovarian cancer cells via STAT3 activation." (PMID 32872659, 2020). "COL11A1 promotes chemoresistance in ovarian cancer; COL11A1 increases the expression of TWIST1, a master EMT regulator directly involved in generating a breast CSC phenotype." (PMID 31334229, 2019). "TWIST1 expression is stabilized by E12; the expression of both TWIST1 and E12 is induced by hypoxia/HIF-1, thus favoring mesenchymal differentiation of ovarian cancer stem cells." (PMID 29389895, 2018).
ovarian carcinoma (continued). "The same group also profiled mesothelial clearance–competent and –incompetent ovarian cancer cell lines and concluded that mesenchymal genes, including SNAI1, ZEB1, and TWIST1 are enriched in the clearance-competent cells." (PMID 29861857, 2018). "DNM3OS has been reported to be a transcriptional target of TWIST1, which regulates ovarian cancer EMT40,41, and was overexpressed in the mesenchymal subtype of ovarian cancer." (PMID 29150601, 2017). "In ovarian cancer cells, MUC4 overexpression upregulates Snail, focal adhesion kinase (FAK), Twist1/2, and MAPK signaling cascade proteins and downregulates E-cadherin and CK18 expression." (PMID 26356073, 2015). "FAM64A exerts its oncogenic function by regulating TWIST1 ubiquitination and degradation, indicating that FAM64A may provide a promising therapeutic target for the treatment of ovarian cancer." (PMID 40424038, 2025). "Notably, COL11A1 has been shown to induce chemoresistance to cisplatin and paclitaxel in ovarian cancer cells through the AKT and Twist1 pathways." (PMID 37207166, 2023). "β-catenin downregulation and degradation are observed in non-stem ovarian cancer cells and are positively correlated with TWIST1, which promotes the upregulation of AXIN2, one of the components of the β-catenin destruction complex." (PMID 36123378, 2022). "Similar to previous reports, the presence of the proteasome inhibitor MG132 blocked TWIST1 degradation in all ovarian cancer cells, primarily in primary EOC cells that did not express TWIST1." (PMID 36123378, 2022). "Collectively, our results show for the first time that LPA induces DDR2 expression and consequent ovarian cancer cell invasion through the HIF-1α and Twist1 signaling axes, reinforcing the significance of LPA and the transactivation between GPCR and RTK in ovarian cancer progression." (PMID 34065317, 2021). "Interestingly, the ovarian cancer patient profiles appeared to positively correlate with ATX (ENPP2) and Twist1 (TWIST1) expression in the GEPIA dataset (r = 0.22, p = 5.1 × 10−7)." (PMID 34065317, 2021). "Indeed, it has been shown that TTP negatively regulates EMT in ovarian cancer cells through binding the SNAIL1 and TWIST1 mRNAs and enhancing their degradation." (PMID 32759946, 2020). "Moreover, our previous report on a panel of 43 ovarian cancer cell lines also showed that SNAI1 expression is enriched in cell lines with E and IE phenotypes, whereas expressions of TWIST1 and ZEB1/2 are higher in cell-line IM and M phenotypes." (PMID 32370157, 2020). "Therefore, overall, our results indicate lncRNA participate in ovarian cancer cell EMT, and specifically, increased DNM3OS expression by amplification or by TWIST1 overexpression contributes to EMT in ovarian cancer." (PMID 29150601, 2017). "Similarly, promotion of EMT by hematopoietic PBX interacting protein, NANOG, TWIST1, SNAI1 FOXM1 accompanied acquisition of ovarian cancer cell resistance to conventional therapeutic agents, such as cisplatin, carboplatin or paclitaxel." (PMID 28792442, 2017). "To further investigate the mechanism by which C17orf91 elicited its oncogenic role, we explored whether C17orf91 could regulate key pro-metastatic genes, such as KLF8, MYC, SNAI2, TWIST1, ZEB1 and ZEB2 in ovarian cancer." (PMID 27535740, 2016). "Ovarian CSCs could be a source of ovarian cancer metastasis through EMT and regulation of TWIST-1 expression, and function is a critical step in this process." (PMID 26718286, 2015). "However, when the levels of TWIST1 protein increase, we found that EOC stem cells differentiate into the migratory ovarian cancer stem cells (mOSC cells) with mesenchymal characteristics." (PMID 25238494, 2014). "In CD44+MyD88+ ovarian CSC/TICs from either ovarian cancer tissues or ovarian ascites, hypoxia/HIF-1 is an extracellular signal that may initiate differentiation of CSC/TICs by triggering TWIST1 expression." (PMID 23528891, 2013).